IKBKE-AS1 (IKBKE antisense RNA 1)
Synonyms: C1orf147; FLJ32597
Gene: Long non-coding RNA gene on chromosome 1 (206,491,116 to 206,497,728, reverse strand). Ensembl gene ENSG00000162888.
Diseases named in the same sentence as IKBKE-AS1 in open-access papers:
IKBKE-AS1 is named in the same sentence as 1 disease in open-access papers, as found by Europe PMC text mining. Sharing a sentence is not in itself a finding about the gene and the disease.
IKBKE-AS1 shares sentences with these, for which no sentence is quoted: tumour (1 paper).